BIVM-ERCC5 (BIVM-ERCC5 readthrough)
Synonyms: ERCC5-202
Gene: Protein-coding gene on chromosome 13 (102,799,110 to 102,875,994, forward strand). Ensembl gene ENSG00000270181.
Genetic constraint (gnomAD): Loss-of-function variants: 93 observed, 166.64 expected, observed/expected ratio (o/e) 0.56, 90% interval 0.47 to 0.66. The upper end of that interval is the gene's LOEUF score, 0.66, which puts it in group 2 of 6, group 1 being the genes least tolerant of losing a copy. Missense variants: 1,827 observed, 2,039.5 expected, observed/expected ratio (o/e) 0.9, 90% interval 0.86 to 0.93. Synonymous variants: 696 observed, 739.75 expected, observed/expected ratio (o/e) 0.94, 90% interval 0.88 to 1.